PPBP (pro-platelet basic protein)
Description:
LA-PF4 stimulates DNA synthesis, mitosis, glycolysis, intracellular cAMP accumulation, prostaglandin E2 secretion, and synthesis of hyaluronic acid and sulfated glycosaminoglycan. It also stimulates the formation and secretion of plasminogen activator by human synovial cells. NAP-2 is a ligand for CXCR1 and CXCR2, and NAP-2, NAP-2(73), NAP-2(74), NAP-2(1-66), and most potent NAP-2(1-63) are chemoattractants and activators for neutrophils. TC-1 and TC-2 are antibacterial proteins, in vitro released from activated platelet alpha-granules. CTAP-III(1-81) is more potent than CTAP-III desensitize chemokine-induced neutrophil activation.
Synonyms: PBP; LDGF; MDGF; CTAP-III; Beta-TG; NAP-2; CTAP3; CXCL7; SCYB7; TGB1; THBGB1; TGB; NAP-2-L1; LA-PF4; b-TG1; CTAPIII; TC1; TC2; THBGB
Tractability: Small molecule: a structure with a bound ligand is known; it has a high-quality binding pocket. Antibody: its Gene Ontology location is reachable by antibodies, with high confidence; UniProt places it where antibodies can reach, with medium confidence; UniProt predicts a signal peptide or a membrane-spanning region.
Gene: Protein-coding gene on chromosome 4 (73,985,966 to 73,988,276, reverse strand). Ensembl gene ENSG00000163736.
Subcellular location: Secreted
Pathways (Reactome):
Signal Transduction: Chemokine receptors bind chemokines; G alpha (i) signalling events
Hemostasis: Platelet degranulation
Immune System: Neutrophil degranulation
Gene Ontology:
Molecular function: protein binding; chemokine activity; CXCR chemokine receptor binding; D-glucose transmembrane transporter activity
Biological process: antimicrobial humoral immune response mediated by antimicrobial peptide; cellular response to lipopolysaccharide; D-glucose transmembrane transport; inflammatory response; neutrophil chemotaxis; chemotaxis; defense response; immune response
Cellular component: extracellular region; platelet alpha granule lumen; tertiary granule lumen
Genetic constraint (gnomAD): Loss-of-function variants: 9 observed, 8.87 expected, observed/expected ratio (o/e) 1.01, 90% interval 0.61 to 1.7. That is too few expected variants to judge how well the gene tolerates losing a copy. Missense variants: 169 observed, 156.75 expected, observed/expected ratio (o/e) 1.08, 90% interval 0.95 to 1.23. Synonymous variants: 64 observed, 62.42 expected, observed/expected ratio (o/e) 1.03, 90% interval 0.84 to 1.26.
Homologues: Orthologues: chimpanzee PPBP (99% identical), macaque PPBP (95% identical), pig PPBP (55% identical), dog PPBP (53% identical), mouse Ppbp (47% identical), rat Ppbp (44% identical), zebrafish cxcl20 (22% identical), zebrafish cxcl18b (15% identical). Paralogues in human: CXCL1 (41% identical), CXCL2 (39% identical), CXCL5 (38% identical), CXCL3 (38% identical), CXCL6 (34% identical), PF4 (34% identical), PF4V1 (33% identical), CXCL8 (30% identical), CXCL9 (23% identical), CXCL13 (21% identical), CXCL10 (20% identical), CXCL11 (17% identical).
Diseases named in the same sentence as PPBP in open-access papers:
PPBP is named in the same sentence as 162 diseases in open-access papers, as found by Europe PMC text mining. Sharing a sentence is not in itself a finding about the gene and the disease. The quoted sentences say what the papers report.
breast carcinoma (21 papers, 2010 to 2025). "The role of VWF, PRG4, and PPBP on breast cancer is predicted to be on tumor progression and metastasis." (PMID 37268731, 2023). "Using this methodology, we identified nine proteins—FN1, VWF, PRG4, MMP9, CLU, PRDX6, PPBP (CXCL7), APOC1, and CHL1—that were robustly quantified in serum and showed statistically significant differences between breast cancer patients and healthy controls." (PMID 40940928, 2025). "PPBP, also known as chemokine CXCL7, is involved in the stimulation of PI3K/Akt signaling and known to promote breast cancer progression." (PMID 38671536, 2024).
COVID-19 (16 papers, 2020 to 2025). A disease caused by infection with severe acute respiratory syndrome coronavirus 2. "Platelet factor 4 (PF4) and platelet-expressing chemokines pro-platelet basic protein (PPBP) were reported significantly downregulated in severe COVID-19 patients, which associated with platelet degranulation and potently contributed to thrombopenia." (PMID 35903092, 2022). "The top up-regulated genes after exposure to COVID-19 during pregnancy included ras-associated protein-1 GTPase-activating-protein (RAP1GAP), pro-platelet basic protein (PPBP), and histone cluster 1, H1b (HIST1H1B)." (PMID 35547542, 2022). "Moreover, PPBP has also been identified as a biomarker for other diseases, such as cancers (e.g. gastric cancer and thyroid carcinoma), inflammation (e.g. rheumatoid arthritis), neurosyphilis, COVID-19, and metabolic disease (e.g. diabetes mellitus)." (PMID 35734636, 2022). "Increased expression of genes related to platelet activation, including PPBP/CXCL7, has been shown in coronavirus disease 2019 (COVID-19) patients." (PMID 37294500, 2024). "In particular, upregulation of PPBP, CXCL7, and SELPLG was considered as biomarkers for intubation in COVID-19 patients." (PMID 35284964, 2022). "The expression of cell-specific genes such as FCER1A in monocyte-derived dendritic cells, PPBP in megakaryocyte, ITGB3 in NK cells, and PF4 in T cells of COVID-19 patients was obviously lower than that in healthy controls." (PMID 36403042, 2022). "In regard to cytokines and chemokine expression between COVID-19 cases we found that the highest avg (log2) values showing fold change were indicated by CCL5, IL1R2, NAMPT and PPBP." (PMID 34824360, 2021).
lung carcinoma (12 papers, 2013 to 2024). "Combined with PADI4 expression, PPBP expression may be considered a non-invasive multi-marker approach offering diagnostic and clinical value in patients with suspected lung cancer." (PMID 38612651, 2024). "This indicates that free DNA is the most useful diagnostic marker for lung cancer and that the combination of DNA with either PPBP and PADI4 or COX2 could improve diagnostic accuracy, especially of early stage tumors." (PMID 23468981, 2013). "A circulating cfDNA analysis combined with the determination of pro-platelet basic protein (PPBP) and PAD4 expression can effectively distinguish healthy donors from NSCLC patients, which may facilitate early lung cancer diagnosis or screening detection." (PMID 36365233, 2022). "Finally, pro-platelet basic protein (PPBP), also known as CXCL7, is a biomarker of several cancer types, such as renal cell cancer, lung cancer and colorectal cancer." (PMID 33323544, 2020). "PPBP is a survival-related hub gene in lung adenocarcinoma and non-smoker females with lung cancer." (PMID 35676660, 2022).
pancreatic cancer (10 papers, 2011 to 2025). "However, serum PPBP levels have been reported to be decreased in pancreatic cancer and ovarian cancer." (PMID 35797333, 2022).
glioma (9 papers, 2019 to 2025). A benign or malignant brain and spinal cord tumor that arises from glial cells (astrocytes, oligodendrocytes, ependymal cells). "A subsequent study by the same authors has shown that glioma-derived FGL2 induces secretion of PPBP (CXCL7) by a subset of TAMs following activation of FGL2/CD16/PI3K/Akt/HIF1α signalling, which promotes the expression of stem-like properties in glioma cells (Molecular event 23)." (PMID 36555253, 2022).
Sepsis (9 papers, 2018 to 2026). Sepsis is defined as life-threatening organ dysfunction caused by a dysregulated host response to infection. "Genes promoting sepsis progression including CLOCK, PPBP and Rho family GTPASE 2 (RND2) were upregulated in Native Hawaiian patients." (PMID 36450776, 2022).
diabetes (8 papers, 2018 to 2024). "Specifically, genes and cell surface markers involved in trans-endothelial migration and the recruitment of CD163+ monocytes were significantly suppressed and the expression of chemokine receptors CX3CR1, CXCL7 (PPBP), and CCR5 were down-regulated in those with diabetes complications." (PMID 39337580, 2024). "Short disease duration without diabetes complications perhaps also helps to explain why the baseline elevations of PPBP, THBS1, and CDH1 were modest in this T2D population, though may additionally indicate that they are more sensitive markers of AIS due to LVO." (PMID 34926573, 2021).
ovarian carcinoma (8 papers, 2009 to 2024). A malignant neoplasm originating from the surface ovarian epithelium. "For example, the chemokine PPBP (pro-platelet basic protein), also known as CXCL7, is decreased in pancreatic and ovarian cancers." (PMID 31242667, 2019). "PPBP was a secreted protein found up-regulated in the mouse plasma, but not discovered in the ovarian cancer cell lines, while CD14 and NRCAM were cell surface proteins from the ovarian cancer cell lines, and were not quantified in mouse plasma." (PMID 19936259, 2009).
colon cancer (7 papers, 2012 to 2022). "Overexpression of PPBP affects the PI3K/AKT/mTOR signaling pathway and is associated with poor prognosis for colon cancer." (PMID 36293321, 2022). "In contrast, PPBP transcript expression was significantly (p < 0.001) upregulated (Log2 fold change = 2.803) in aggregate colon cancer data and in two of the cohorts." (PMID 35560039, 2022).
colorectal cancer (7 papers, 2019 to 2025). A primary or metastatic malignant neoplasm that affects the colon or rectum. "In colorectal cancer, the expression of PPBP was significantly correlated with sex, TNM and T stages." (PMID 33323544, 2020). "Further analysis showed that differentially expressed genes such as PPBP, CCL28, and CXCL12 are likely to be involved in the development of colorectal cancer and may be potential diagnostic and therapeutic targets." (PMID 32797167, 2020).
gastric cancer (7 papers, 2016 to 2025). A primary or metastatic malignant neoplasm involving the stomach. "Some studies have indicated that PPBP and its encoded proteins might be linked to the progression of Wilms tumor and gastric cancer." (PMID 34976004, 2021). "PPBP has been involved in various cellular processes and malignancies; in fact, it has been found to be down-regulated in the plasma of patients with gastric cancer (GC), and has been suggested to be a diagnostic biomarker of that disease." (PMID 38339034, 2024). "PPBP and its chemokine CXCL7 influence tumor biology via CXCR1/2 binding and were proposed as early lung and gastric cancer biomarkers." (PMID 40297587, 2025). "For gastrointestinal cancer, the prognostic value of CEBPA-DT was illustrated along with several other lncRNAs (INHBA-AS1, AK001058, UCA1, PPBP, and RGS18) in early gastric cancer." (PMID 36471363, 2022).
rheumatoid arthritis (7 papers, 2016 to 2022). A chronic, systemic autoimmune disorder characterized by inflammation in the synovial membranes and articular surfaces. "Intriguingly, PPBP (CXCL7) and PF4 (CXCL4) belong to the CXC chemokine family, which plays a pivotal role in the development or progression of rheumatoid arthritis (RA), antiphospholipid syndrome, and systemic lupus erythematosus." (PMID 34867780, 2021).
asthma (6 papers, 2017 to 2025). "Tissue specificity was evident: megakaryocytes (PPBP+, Cluster 15) were exclusive to asthma PBMCs (2.1% of cells), while macrophages (CD68+, Cluster 18) dominated AD CSF (8.7% vs." (PMID 40951943, 2025). "Pro-Platelet Basic Protein (PPBP), another highly connected gene in our network, has been identified as a potential placental biomarker for PE and asthma in the literature." (PMID 33046794, 2020).
chronic obstructive pulmonary disease (4 papers, 2012 to 2024). A chronic and progressive lung disorder characterized by the loss of elasticity of the bronchial tree and the air sacs, destruction of the air sacs wall, thickening of the bronchial wall, and mucous accumulation in the bronchial tree. "Increased PPBP/CXCL7 chemokine expression has been associated with neutrophil activation in patients with severe stable chronic obstructive pulmonary disease." (PMID 31373289, 2019).
clear cell renal carcinoma (4 papers, 2018 to 2024). A malignant epithelial neoplasm of the kidney characterized by the presence of lipid-containing clear cells within a vascular network. "In clear cell renal carcinoma, serum PPBP has been reported to be a predictive marker of sunitinib efficacy." (PMID 35797333, 2022).
hyperlipidemia (4 papers, 2017 to 2024). "Like PF4 and CXCL5, PPBP has received little research attention in the context of ICH, but is considered a potential risk factor for coronary heart disease in patients with hyperlipidemia." (PMID 38271077, 2024). "The present study aimed to determine the values of the PPBP and DEFA1/DEFA3 genes and their encoded proteins as biomarkers of CHD risk in postmenopausal Thai women with hyperlipidemia." (PMID 35734636, 2022). "Our findings suggest the possibility of applying the plasma proteins PPBP and α-defensin 1–3 as CHD risk markers in hyperlipidaemia patients." (PMID 28420383, 2017). "Based on these data, we suggest that significantly increased expression of both PPBP and DEFA1/DEFA3 and their encoded proteins has the potential to be established as a synergistic predictive biomarker for CHD risk in hyperlipidaemia patients." (PMID 28420383, 2017). "We recently reported that the PPBP and DEFA1/DEFA3 genes could act as biomarkers for CHD risk in Thai men with hyperlipidemia." (PMID 35734636, 2022). "We recently reported that the PPBP and DEFA1/DEFA3 genes may be feasible synergistic biomarkers for CHD risk in Thai men with hyperlipidemia." (PMID 35734636, 2022). "The results indicate that gene and protein expression levels of PPBP, but not DEFA1/DEFA3, and HNP-1–3, may be feasible biomarkers for assessing CHD risk in postmenopausal Thai women with hyperlipidemia." (PMID 35734636, 2022). "PPBP and DEFA1/DEFA3 could be potential CHD biomarkers in Thai hyperlipidaemia patients." (PMID 28420383, 2017). "A few human studies have provided a promising link of differential gene expression in hyperlipidemia with inflammation and CAD, although there are no current drug therapies targeting these genes such as pro-platelet basic protein (PPBP) and α-defensin (DEFA1/DEFA3)." (PMID 38255639, 2023).
leukemia (4 papers, 2017 to 2025). A malignant (clonal) hematologic disorder, involving hematopoietic stem cells and characterized by the presence of primitive or atypical myeloid or lymphoid cells in the bone marrow and the blood. "Notably, each of these proteins has a plausible link to leukemia biology (for example, CXCL7/PPBP is a platelet-derived factor that can modulate hematopoiesis, and ENO1 is a metabolic enzyme often upregulated in cancer cells)." (PMID 40831732, 2025). "It should be noted that, on the contrary, current studies have also found that the expression of PPBP in different types of leukemia may also be significantly different, and PPBP may be lower-expressed in AML-M4." (PMID 34148032, 2021).
liver fibrosis (4 papers, 2018 to 2023). "PPBP is a small protein produced by monocytes, macrophages, and mainly platelets, and thus the decrease in PPBP levels in EVs and serum may be associated with the decrease in platelet counts due to the progression of liver fibrosis." (PMID 35797333, 2022). "We evaluated the correlations among serum SAP and PPBP levels and the levels of other reported liver fibrosis markers, namely, type IV collagen 7S and hyaluronic acid." (PMID 35797333, 2022). "Although the relationship between PPBP levels and platelet counts or IL-10 levels requires further investigation, we have revealed for the first time that serum PPBP levels decrease with the progression of liver fibrosis." (PMID 35797333, 2022). "SAP and PPBP levels in serum as well as in EVs are novel biomarkers of liver fibrosis in chronic hepatitis C patients." (PMID 35797333, 2022). "One targeted proteomics study using extracellular vesicles highlights that levels of APCS and pro-platelet basic protein were significantly decreased in liver fibrosis progression, patients with liver cirrhosis, acute hepatitis and non-alcoholic fatty liver disease patients." (PMID 37349331, 2023). "Proteomic analysis of serum extracellular vesicles showed that PPBP could represent a potential biomarker of liver fibrosis in patients with chronic hepatitis C." (PMID 37122736, 2023). "We performed a comprehensive analysis of serum-derived EV proteins in chronic hepatitis C patients and clarified for the first time that SAP and PPBP in EVs could be markers of liver fibrosis." (PMID 35797333, 2022). "In addition, PPBP expression is reportedly regulated by the anti-inflammatory cytokine IL-10, suggesting that the decrease in PPBP levels with the progression of liver fibrosis also reflects the increase in IL-10 production in response to the progression of fibrosis." (PMID 35797333, 2022). "In conclusion, proteomic analysis of serum EVs identified SAP and PPBP as candidate biomarkers for predicting liver fibrosis in patients with chronic hepatitis C. In addition, SAP and PPBP levels in serum are strongly correlated with those in EVs and could represent markers of liver fibrosis." (PMID 35797333, 2022). "Along with the progression of liver fibrosis, IGHV, GAPDH, C1s, GRP78 and V-ATPase levels significantly increased, and PPBP, CD9, Lp(a) and SAP levels significantly decreased." (PMID 35797333, 2022). "Moreover, serum SAP and PPBP levels correlated with the levels in EVs, and the ability of serum SAP and PPBP to diagnose liver fibrosis stage was also comparable to the abilities of type IV collagen 7S, hyaluronic acid, and the FIB-4 index." (PMID 35797333, 2022). "We identified that SAP and PPBP levels in EVs decreased as liver fibrosis progressed by proteomic analysis in patients with chronic hepatitis C. Serum SAP and PPBP levels were strongly correlated with those in EVs and decreased as liver fibrosis progressed." (PMID 35797333, 2022). "On the other hand, serum PPBP levels were significantly decreased with the progression of liver fibrosis in patients with NAFLD, but not in patients with chronic hepatitis B." (PMID 35797333, 2022). "However, in the present study, PPBP levels decreased with liver fibrosis progression, and we postulate that PPBP does not exert a substantial effect on fibrosis formation, but simply reflects fibrosis." (PMID 35797333, 2022).
lung adenocarcinoma (4 papers, 2018 to 2025). A carcinoma that arises from the lung and is characterized by the presence of malignant glandular epithelial cells. "In liver hepatocellular carcinoma and lung adenocarcinoma, CXCL2 and PPBP negatively correlated with proliferation, and were the only CXCR2 ligands that negatively correlated with the count of MDSCs." (PMID 37686093, 2023).
renal cell carcinoma (4 papers, 2019 to 2022). "PPBP has been reported to be up-regulated in the peripheral blood of early-stage renal cell carcinoma patients." (PMID 33323544, 2020).
Stroke (4 papers, 2020 to 2023). Sudden impairment of blood flow to a part of the brain due to occlusion or rupture of an artery to the brain. "In summarizing this study, we affirm that our risk assessment model, based on PADGs, specifically APP, THBS1, F13A1, SRC, PPBP, and VCL, presents robust diagnostic capabilities for stroke patients." (PMID 38268925, 2023).
vitiligo (4 papers, 2020 to 2024). Generalized well circumscribed patches of leukoderma that are generally distributed over symmetric body locations and is due to autoimmune destruction of melanocytes. "We found significant upregulation of CCL5 and CXCL10, as well as CXCL7 (gene name PPBP) in canine VKH and vitiligo." (PMID 33384688, 2020).
Arthritis (3 papers, 2016 to 2022). Inflammation of a joint. "Based on the IPA analysis BmA pre-exposure before LPS E. coli re-stimulation affected several pathways like granulocyte and agranulocyte adhesion and diapedesis (PPBP/CXCL7, PECAM1, CCL20, CXCL5, CXCL6, MMP9), IL-17 in psoriasis, arthritis and signaling in airway cells (CCL20, CXCL5, CXCL6)." (PMID 30796272, 2019).